CD4 (CD4 molecule)
Diseases named in the same sentence as CD4 in open-access papers (continued):
Sharing a sentence is not in itself a finding about the gene and the disease.
AIDS (continued). "After disseminating to secondary lymphoid organs and peripheral tissues, a systemic inflammatory response ensues, leading to a viral set point maintained until significant CD4 + T cell loss results in acquired immunodeficiency syndrome (AIDS)." (PMID 39609320, 2024). "One of three recipients of the third serial passage displayed sustained plasma viral loads >106 viral RNA copies/mL for 28 weeks, with progressive loss of CD4+ T cells in blood and the development of an AIDS-defining extranodal B-cell lymphoma." (PMID 39459950, 2024). "Human immunodeficiency virus type 1 (HIV-1) causes a chronic infection leading to AIDS via infecting CD4 receptor-expressing (CD4+) immune cells." (PMID 39107318, 2024). "This is followed by a chronic infection that results in massive CD4+ T-cell depletion by apoptosis and pyroptosis, which is known as acquired immune deficiency syndrome (AIDS)." (PMID 39062562, 2024). "HIV is known to be responsible for acquired immune deficiency syndrome (AIDS) due to loss of CD4+ T-lymphocytes, with the consequent defects in immune system activity." (PMID 38939361, 2024). "CD8+ count has been associated with inflammatory non-AIDS-related clinical events, and the CD4/CD8 ratio is increasingly recognized as an important marker of immune reconstitution." (PMID 39742334, 2024). "HIV-1 significantly impacts the T cell compartment, leading to AIDS through persistent CD4 + T cell loss." (PMID 39609320, 2024). "Ultimately, the decline in CD4 + levels predisposes patients with AIDS to a higher risk of opportunistic infections due to pathogens." (PMID 37430367, 2023). "The dose response association of common comorbid diseases with lower CD4 count underscores the likely role of HIV in non-AIDS conditions and warrants further exploration." (PMID 38356736, 2023). "HIV/AIDS infected patients have a higher risk of opportunistic infections (OIs) depending on their immunological status, especially CD4 cell count." (PMID 36840494, 2023). "Specifically, a CD4/CD8 ratio < 0.5 or < 0.3 has been determined to be a risk factor for non-AIDS events or mortality, especially when the CD4 count is high (≥ 500 cells/μL)." (PMID 36627565, 2023). "These individuals with higher T-cell activation display slow but progressive CD4+ T-cell loss and can develop AIDS, emphasizing the role of immune activation in the pathogenesis of HIV-1 infection." (PMID 36672667, 2023). "In fact, in addition to the absolute number and percentage of CD4+ T cells, they represent strong predictors of the risk of non-AIDS events and mortality in HIV-1 patients undergoing antiretroviral therapy." (PMID 36672667, 2023). "While liver inflammation is associated with AIDS, little is known so far about hepatic CD4+ T cells." (PMID 37656815, 2023). "The virus targets CD4+ T cells, macrophages and dendritic cells, leading to their depletion and dysfunction, with a CD4+ T cell count below 200 cells/mm3 considered diagnostic of AIDS." (PMID 37408185, 2023). "Several other studies have also shown that hematological abnormalities in hemoglobin, HCT, and MCV were prevalent among HIV/AIDS patients and associated with CD4+ T cell count." (PMID 37736888, 2023). "Early work had shown HIV-1 infection induced pathogenic CD4 T cell death, a hallmark during the progression to AIDS in HIV and SIV." (PMID 36780482, 2023). "Persistent CD4:CD8 ratios less than 0.3 have been shown to be independently associated with increased risk of non-AIDS-related events and mortality." (PMID 36851599, 2023). "Despite the low mortality rate in patients on cART with a sustained virological response, a higher CD4 cell count is always associated with a reduced risk of a new AIDS event or death." (PMID 37375012, 2023). "HIV infection can lead to immune deficiency in the human body, and when the CD4+ T lymphocyte count drops below 200 cells/μL, the condition is termed AIDS." (PMID 38126075, 2023).
AIDS (continued). "The TLR8 variants with weak activity are related to slow decrease of CD4+ T cell and clinical progression of AIDS in HIV-1 infected individuals." (PMID 37134013, 2023). "HIV/AIDS-associated neurocognitive impairments negatively affect treatment adherence, viral load suppression, CD4 count, functionality, and the overall quality of life of people with seropositive status." (PMID 37254121, 2023). "The common association between these studies is that hypoalbuminemia, defined as albumin concentrations <34 g/L, along with a CD4+ T cell count below 500 cells/mm3, are associated with more rapid progression of AIDS." (PMID 37736888, 2023). "Clinical researchers found that the majority of T.marneffei-infected HIV patients had less than 50 CD4+T cell counts, and it had certain diagnostic efficacy for early AIDS combined with the T.marneffei infection." (PMID 38148912, 2023). "Previous studies have also indicated that CD4+ counts <50 cells/μL are significant risk factors for the development of CMVR in AIDS patients." (PMID 37305416, 2023). "GL not only inhibits HIV but also induces interferon production, enhances natural killer C effects, and increases the number of CD4-positive T lymphocytes to effectively prevent the development of acquired immune deficiency syndrome (AIDS)." (PMID 37242424, 2023). "Human immunodeficiency virus (HIV/AIDS) infected patients have a higher risk of opportunistic infections (OIs) depending on their immunological status, especially CD4 + cell count." (PMID 36840494, 2023). "The levels of CD4 lymphopaenia seen in PLA patients resemble those seen in AIDS where CD4 counts <0.2x109/L are associated with opportunistic infections." (PMID 38022535, 2023). "For example, CD4+ T-cell deficiency in patients with AIDS increases the likelihood of lung infection." (PMID 37564654, 2023). "On this basis, we analyzed the association of these tSNPs with CD4+ T cell counts and AIDS clinical stages." (PMID 37468905, 2023). "If we attribute mortality with unconfirmed cause in participants who met immunologic criteria for AIDS (CD4 < 200 cells/μL) to HIV, the HIV-related causes would be responsible for more than half of all deaths among index participants." (PMID 37170118, 2023). "Across the subcategories, the highest mortality was among participants who met diagnostic criteria for AIDS, i.e. had a CD4 count of < 200 cells/μL (CMR, 20.8 [14.8–28.4]; SMR, 60.6 [43.1–82.8])." (PMID 37170118, 2023). "This is one of the earliest functional defects observed in chronic PLHIV and predicts the loss of CD4+ T cells and the progression of AIDS." (PMID 37608956, 2023). "Another limitation of our studies is that it remains unadjusted for HIV-specific factors that are associated with risk of renal impairment, including a prior AIDS-defining illness, nadir CD4+ count and current CD4+ count." (PMID 36827395, 2023). "CD4 is the receptor of the HIV envelope protein gp120; thus, HIV can selectively infect CD4 + T cells to cause AIDS." (PMID 37644056, 2023). "Another observation supporting the role of immune activation as the major driving force of CD4+ T-cell loss and AIDS is provided by the elite controller group (ECs)." (PMID 36672667, 2023). "In this sense, a low CD4/CD8 ratio has been associated with an increased risk of non-AIDS-related events and death." (PMID 36769822, 2023). "This difference is due to the decrease in the number of CD4+ T lymphocytes caused by AIDS, which prevents the effective formation of granuloma in MTB infection." (PMID 37110574, 2023). "Systemic chronic immune activation and CD4+ T-cell depletion characterize the progression of human immunodeficiency virus type-1 (HIV-1) infection toward acquired immune deficiency syndrome (AIDS)." (PMID 36672667, 2023). "HIV-associated or AIDS-defining conditions had previously been diagnosed in 56 participants (66%), the median CD4-nadir was 173/μl (range 0–922)." (PMID 37526898, 2023).
AIDS (continued). "Generally, there is a progressive decline in CD4+ levels in AIDS, which causes a decrease in both humoral and cell-mediated immunity." (PMID 37430367, 2023). "The most frequent predisposing factor of CDS was HIV-AIDS, usually occurring in patients in stage C of AIDS (CD4+ count <200 cells/ mm3)." (PMID 37721953, 2023). "It was consistent with the previous study that the elevated serum AST was determined as the independent risk factors for poor outcome in AIDS patients complicated with T. marneffei and the poor outcome group had significantly lower CD4+ T cell count." (PMID 37011093, 2023). "The association of comorbid diseases with lower CD4 underscores the likely role of HIV in non-AIDS conditions." (PMID 38356736, 2023). "Depression has been shown to be associated with myriad adverse health outcomes for PLWH, including lower CD4 count, higher viral load, lower medication adherence, and AIDS-related and all-cause mortality." (PMID 37084105, 2023). "Only 14.9% of women had CD4 counts <200 per mm3 and 17% were at the Acquired Immuno Deficiency Syndrome (AIDS) stage." (PMID 38234591, 2023). "Slow AIDS progression is associated with haplogroup H and better CD4+ T-cell reconstruction, whereas haplogroups J and T are associated with poor CD4+ T-cell recovery." (PMID 37649488, 2023). "Cox proportional hazards model analysis indicated that ART, baseline CD4 count level, age of diagnosis, education, and screening way remained statistically significantly associated with AIDS-related death." (PMID 36339239, 2022). "In line with observations of CSF cytokines, it was reported that higher secretions of IFN-γ and TNF-α by peripheral CD4+ T cells were associated with improved survival of HIV/AIDS patients with cryptococcal meningoencephalitis." (PMID 36557672, 2022). "Another study, which did not analyze patients with acute HIV infection, connected high viral load with an increased risk of AIDS and, thus, inferior rates of CD4 recovery." (PMID 36298842, 2022). "For example, studies have frequently modeled longitudinal CD4 count jointly with time-to-HIV–related outcomes in order to understand the relationships between the longitudinal history of CD4 and its effect on the risk of development of AIDS." (PMID 38455327, 2022). "Human immunodeficiency virus (HIV) is a retrovirus that causes acquired immunodeficiency syndrome (AIDS) by infecting several important immune cell types including CD4+ T lymphocytes and macrophages." (PMID 35693831, 2022). "The adjusted models suggested an increased risk of serious non-AIDS events associated with low CD4/CD8 ratio." (PMID 35428209, 2022). "Infection with the human immunodeficiency virus type 1 (HIV-1) results in the progressive loss of immune function, marked by the depletion of CD4+ T-lymphocytes, leading to opportunistic infections and malignancies characteristic of AIDS." (PMID 35814692, 2022). "AIDS was universally fatal with opportunistic coinfections due to the loss of CD4 T cell–mediated immunity and HIV-associated neurocognitive disorder (HAND), which includes severe HIV-associated dementia (HAD)." (PMID 36278485, 2022). "Mice deficient in CD4 T cells are highly susceptible to TB, and the loss of CD4 T cells in patients suffering from AIDS is strongly correlated with re-activation of dormant M. tuberculosis infection." (PMID 35877763, 2022). "Except for CM, we show here that gender, age, symptoms, CD4 cell count, and VL were significantly associated with the survival of patients with AIDS administered second-line ART." (PMID 35126600, 2022). "Most previous studies used the time from infection to the diagnosis of AIDS or the rate of CD4 loss per year to evaluate the rate of disease progression." (PMID 35260599, 2022). "Overall, we found that route of transmission (sexual exposure), HCV coinfection, diagnosis of AIDS and older age were negatively associated with CD4 cells count." (PMID 36329104, 2022).
AIDS (continued). "In HIV-infected people, lower selenium levels have been associated with lower CD4 T-cell counts, faster progression of AIDS, and a 20% increase in the risk of death." (PMID 35163318, 2022). "Especially, patients with HIV/AIDS with a low CD4 count (CD4 counts <200/μl) are at the highest risk of PCP." (PMID 35308503, 2022). "Traveling to endemic areas or being in contact with guano birds or bats, use of steroids, diabetes mellitus, and HIV/AIDS with CD4 < 150 cells/mm3are risk factors especially in immunocompetent patients." (PMID 35783363, 2022). "Acute infection is characterized by a large initial loss of CD4+ cells with an eventual drop of CD4+ counts to 200 cells/mm3, raising concern for AIDS." (PMID 36146843, 2022). "There are studies indicating that the development of AIDS is associated with poorer rates of CD4 and CD4:CD8 normalization than among patients diagnosed in earlier stages of HIV infection." (PMID 36298842, 2022). "Gender, age, symptoms, CD4 cell counts, and viral loads were independently associated with the survival of AIDS patients treated with second-line ART." (PMID 35126600, 2022). "Low CD4 count and prior AIDS-defining illness were strongly associated with higher hazard ratios of death, especially when considering very early mortality." (PMID 35581552, 2022). "For heterosexuals, the risk of non-AIDS-related deaths greatly exceeded that of homosexuals, likely owing to their lower baseline CD4 + T lymphocytes, more comorbidities and higher WHO clinical stage at ART initiation." (PMID 35346084, 2022). "CM, gender, age, symptoms, CD4 cell count, and VL were independently associated with mortality of patients with AIDS administered second-line ART." (PMID 35126600, 2022). "In the case of cryptococcosis, HIV+/AIDS patients are the most susceptible population, and γδ T cells have been shown to remain functional in reported cases of human of CD4-lymphopenia." (PMID 36229573, 2022). "Due to the viral tropism towards host immune cells, HIV infection leads to critically low levels of CD4 + T cells, thus causing acquired immunodeficiency syndrome (AIDS) and increasing susceptibility to opportunistic infections." (PMID 36088417, 2022). "Low CD4+ T-cell count increases the risk of morbidity and mortality of AIDS and non-AIDS-related complications even though these patients have reached virological suppression." (PMID 36483196, 2022). "HIV/SIV infection is characterized by the persistent loss of CD4+ T cells, leading to immunodeficiency and subsequently AIDS/SAIDS." (PMID 35778766, 2022). "HIV has a strong attack on the human immune cells dominated by CD4+ T lymphocytes, gradually leading to the damage and loss of the human immune system, and eventually resulting in AIDS-related malignant tumors." (PMID 35694588, 2022). "Cryptococcosis is a severe life-threatening disease and a major cause of mortality in people with advanced AIDS and CD4 ≤ 100 cells/μL." (PMID 36547617, 2022). "The higher prevalence of hyperglycemia in people with advanced HIV should be interpreted in light of previous studies that showed an association between a low CD4 cell count and non-AIDS events." (PMID 36301817, 2022). "The emergence of HIV-1 populations that switch coreceptors from R5 to X4 has been associated with the depletion of CD4+ T cells and disease progression toward acquired immune deficiency syndrome (AIDS)." (PMID 36644395, 2022). "According to the joint model, there was an inverse statistically significant association between the probability of AIDS‐related mortality and the percentage of CD4 (%CD4) during the time to follow up and (HR:0.9 [CI95%, 0.86‐0.98], p=0.046)." (PMID 35916394, 2022). "The AIDS patient becomes susceptible to opportunistic infectious diseases,like candidiasis, due to the invasion of this virus into CD4+ lymphocytes and the destruction of these cells that play a role in commanding the cellular defense system." (PMID 36654790, 2022).
AIDS (continued). "As HIV/AIDS is associated with deranged immunologic status, participants with a lowered CD4 cell count (below 500 cells/μL of blood) were almost 7 times (6.561) compared to those whose immunity had greater CD4 cell counts (> 500 cells/μL of blood)." (PMID 36762162, 2022). "It is notable that low CD4/CD8 ratios have been associated with increased risk of non-AIDS-related events and death." (PMID 36366413, 2022). "The Italian Vaccination Plan included in the priority category for anti-COVID-19 vaccination HIV-infected patients with acquired immune deficiency syndrome (AIDS) or CD4+ count <200 cells/mm3." (PMID 36016131, 2022). "Persistently low CD4 + T cell counts are associated with an increased risk of both AIDS-related and non-AIDS-related morbidity and mortality." (PMID 35135485, 2022). "In AIDS patients, the prevalence of sexually transmitted infections (STIs) and the severity of other infections are associated with CD4+ T cell counts." (PMID 36067140, 2022). "Given that HIV/AIDS patients are at high risk for cryptococcosis due to CD4+ T cell lymphopenia, the role of type 1 CD4+ polarized T cells in mediating host protection is undeniable." (PMID 36229573, 2022). "There is increasing evidence that it can be used to identify HIV-infected individuals with persistent immune dysfunction who, despite having a normal CD4 count during treatment, have a higher risk of non-AIDS events and death." (PMID 35646738, 2022). "Cryptosporidium infection is common among HIV/AIDS patients (prevalence of 8,69%) worsening the protozoan infection associated symptoms causing severe diarrhea and eventually death because of low CD4+ T-cells counts." (PMID 36504775, 2022). "The susceptibility of HIV/AIDS patients to C. neoformans infection is attributed to impaired cellular immune responses, particularly the quantitative and qualitative defects of CD4+ T cells." (PMID 36557672, 2022). "This is supported by the extreme susceptibility of Ifng-/- and Rag1-/- mice, the high co-morbidity between TB and low CD4 T cell counts caused by AIDS, and the ability of recombinant IFN-γ to control bacterial growth in mouse and human macrophages in vitro." (PMID 35877763, 2022). "Factors that render an individual susceptible include neutropenia, corticosteroid use, hematologic malignancies, diabetes, underlying lung disease, and AIDS, with low CD4 counts being associated with a higher incidence of this condition." (PMID 36212620, 2022). "Untreated, HIV-1 causes a chronic infection that leads to AIDS, characterized by CD4+ T cell depletion that leaves patients vulnerable to opportunistic infections and malignancies." (PMID 35323042, 2022). "Critical loss in CD4 T cell count is a key parameter for defining acquired immunodeficiency syndrome (AIDS)." (PMID 34843064, 2022). "It has been reported that CRF01_AE infection is associated with rapid CD4+ T–cell decline and more likely progression to AIDS than infections of other types." (PMID 35719611, 2022). "After long-term anti-retroviral therapy (ART) treatment, most human immunodeficiency virus (HIV)/Acquired Immure Deficiency Syndrome (AIDS) patients can achieve virological suppression and gradual recovery of CD4+ T-lymphocyte (CD4+ T cell) counts." (PMID 36325329, 2022). "Many previous studies show a beneficial effect of this variant on the number of CD4+ lymphocytes, the rate of immune recovery, and protection against AIDS." (PMID 35407496, 2022). "The risk of developing an AIDS event was three times higher for individuals with CD4/CD8 ratio ≤ 0.4 compared to those with CD4/CD8 ratio > 0.4 among non-late presenters and twice as high in both late and advanced presenters." (PMID 35428209, 2022). "Younger, better educated MSM, and those with lower CD4 counts were more concerned about potential risk of AIDS and potential complications upon trial participation." (PMID 35428275, 2022).